NR5A2 (nuclear receptor subfamily 5 group A member 2)
Description:
Orphan nuclear receptor that binds DNA as a monomer to the 5'-TCAAGGCCA-3' sequence and controls expression of target genes: regulates key biological processes, such as early embryonic development, cholesterol and bile acid synthesis pathways, as well as liver and pancreas morphogenesis. Ligand-binding causes conformational change which causes recruitment of coactivators, promoting target gene activation. The specific ligand is unknown, but specific phospholipids, such as phosphatidylethanolamine, phosphatidylserine, dilauroyl phosphatidylcholine and diundecanoyl phosphatidylcholine can act as ligand in vitro. Acts as a pioneer transcription factor, which unwraps target DNA from histones and elicits local opening of closed chromatin. Plays a central role during preimplantation stages of embryonic development (By similarity). Plays a minor role in zygotic genome activation (ZGA) by regulating a small set of two-cell stage genes (By similarity). Plays a major role in morula development (2-16 cells embryos) by acting as a master regulator at the 8-cell stage, controlling expression of lineage-specifying transcription factors and genes involved in mitosis, telomere maintenance and DNA repair (By similarity). Zygotic NR5A2 binds to both closed and open chromatin with other transcription factors, often at SINE B1/Alu repeats DNA elements, promoting chromatin accessibility at nearby regulatory regions (By similarity). Also involved in the epiblast stage of development and embryonic stem cell pluripotency, by promoting expression of POU5F1/OCT4. Regulates other processes later in development, such as formation of connective tissue in lower jaw and middle ear, neural stem cell differentiation, ovarian follicle development and Sertoli cell differentiation (By similarity). Involved in exocrine pancreas development and acinar cell differentiation (By similarity). Acts as an essential transcriptional regulator of lipid metabolism. Key regulator of cholesterol 7-alpha-hydroxylase gene (CYP7A) expression in liver. Also acts as a negative regulator of inflammation in different organs, such as, liver and pancreas. Protects against intestinal inflammation via its ability to regulate glucocorticoid production (By similarity). Plays an anti-inflammatory role during the hepatic acute phase response by acting as a corepressor: inhibits the hepatic acute phase response by preventing dissociation of the N-Cor corepressor complex. Acts as a regulator of immunity by promoting lymphocyte T-cell development, proliferation and effector functions (By similarity). Also involved in resolution of endoplasmic reticulum stress in the liver (By similarity). [Isoform 3]: In constrast to isoform 1 and isoform 2, does not induce cholesterol 7-alpha-hydroxylase gene (CYP7A) promoter activity. (Microbial infection) Plays a crucial role for hepatitis B virus gene transcription and DNA replication. Mechanistically, synergistically cooperates with HNF1A to up-regulate the activity of one of the critical cis-elements in the hepatitis B virus genome enhancer II (ENII).
Synonyms: hB1F; LRH-1; B1F; CPF; FTF; FTZ-F1beta; FTZ-F1; hB1F-2; B1F2; LRH1
Tractability: Small molecule: a structure with a bound ligand is known; a high-quality ligand is known; it has a high-quality binding pocket; it belongs to a druggable protein family. PROTAC: UniProt records ubiquitination sites on it; a small molecule that binds it is known.
Target class: Nuclear receptor; Nuclear hormone receptor subfamily 5; Nuclear hormone receptor subfamily 5 group A member 2; Nuclear hormone receptor subfamily 5 group A; Transcription factor
Chemical probes: ML-180, ML179
Gene: Protein-coding gene on chromosome 1 (200,027,597 to 200,177,420, forward strand). Ensembl gene ENSG00000116833.
Subcellular location: Nucleus; Chromosome
Subcellular location (Human Protein Atlas): Nuclear speckles
Pathways (Reactome):
Gene expression (Transcription): MLL4 and MLL3 complexes regulate expression of PPARG target genes in adipogenesis and hepatic steatosis; Nuclear Receptor transcription pathway
Developmental Biology: Regulation of gene expression in early pancreatic precursor cells
Metabolism of proteins: SUMOylation of intracellular receptors
Signal Transduction: Estrogen-dependent gene expression
Gene Ontology:
Molecular function: DNA binding; DNA-binding transcription factor activity; nuclear receptor activity; phospholipid binding; protein binding; sequence-specific DNA binding; sequence-specific double-stranded DNA binding; transcription cis-regulatory region binding; transcription coregulator binding; chromatin binding; DNA-binding transcription factor activity, RNA polymerase II-specific; RNA polymerase II cis-regulatory region sequence-specific DNA binding; double-stranded DNA binding; zinc ion binding
Biological process: bile acid metabolic process; chromatin remodeling; positive regulation of DNA-templated transcription; positive regulation of transcription by RNA polymerase II; positive regulation of viral genome replication; regulation of DNA-templated transcription; embryo development ending in birth or egg hatching; embryonic cleavage; exocrine pancreas development; homeostatic process; hormone-mediated signaling pathway; inner cell mass cell differentiation; morula formation; negative regulation of chondrocyte differentiation; negative regulation of inflammatory response; neurogenesis; positive regulation of glucocorticoid biosynthetic process; positive regulation of stem cell differentiation; positive regulation of T cell activation; positive regulation of T cell anergy; positive regulation of T cell proliferation; positive regulation of tendon cell differentiation; primary ovarian follicle growth; regulation of transcription by RNA polymerase II; Sertoli cell development; and 6 more
Cellular component: chromosome; cytoplasm; nucleus; transcription repressor complex; chromatin; nucleoplasm; RNA polymerase II transcription regulator complex
Genetic constraint (gnomAD): Loss-of-function variants: 24 observed, 54.49 expected, observed/expected ratio (o/e) 0.44, 90% interval 0.32 to 0.62. The upper end of that interval is the gene's LOEUF score, 0.62, which puts it in group 2 of 6, group 1 being the genes least tolerant of losing a copy. Missense variants: 501 observed, 619.36 expected, observed/expected ratio (o/e) 0.81, 90% interval 0.75 to 0.87. Synonymous variants: 218 observed, 225.73 expected, observed/expected ratio (o/e) 0.97, 90% interval 0.86 to 1.08.
Homologues: Orthologues: chimpanzee NR5A2 (100% identical), macaque NR5A2 (99% identical), pig NR5A2 (97% identical), guinea pig NR5A2 (95% identical), rat Nr5a2 (90% identical), dog NR5A2 (89% identical), tropical clawed frog nr5a2 (88% identical), mouse Nr5a2 (84% identical), zebrafish nr5a2 (82% identical), Drosophila melanogaster ftz-f1 (43% identical), Drosophila melanogaster Hr39 (31% identical), Caenorhabditis elegans nhr-25 (30% identical), and 14 more. Paralogues in human: NR5A1 (53% identical).
Diseases named in the same sentence as NR5A2 in open-access papers:
NR5A2 is named in the same sentence as 89 diseases in open-access papers, as found by Europe PMC text mining. Sharing a sentence is not in itself a finding about the gene and the disease. The quoted sentences say what the papers report.
breast carcinoma (28 papers, 2009 to 2025). "Although NR5A2 has been associated with poor prognosis in breast cancer, its role in breast cancer is not fully understood." (PMID 38994678, 2024). "NR5A2 is an estrogen receptor target gene, and NR5A2 is a key regulator of aromatase expression in breast cancer-associated adipose stromal fibroblasts." (PMID 36140779, 2022). "NR5A2 has been described to be associated with invasive breast cancer and is additionally thought to be involved in promotion of migration of breast cancer." (PMID 26627005, 2015). "Moreover, miR-27b levels are also reduced in tamoxifen-resistant breast cancer cell lines as well as patient samples, which are associated with the increased expression of miR-27b targets NR5A2/LRH1 and CREB1." (PMID 30214383, 2018). "The upregulation of miR-27b sensitization to tamoxifen in ER+ breast cancer cells was further associated with the suppression of direct targets, NR5A2/LRH1 and CREB1, which are implicated in tamoxifen resistance via the induction of ERα and aromatase, respectively." (PMID 30214383, 2018). "The expression of NR5A2 variant 4 has been reported in both ER-positive and ER-negative breast cancer cell lines and our analysis of mRNA sequencing data of TCGA invasive breast cancer cohort found that variant 4 was also the predominantly expressed NR5A2 transcript in primary breast cancers." (PMID 29137369, 2017). "We found a positive correlation between HSD3B1 and NR5A2 expression in hormone therapy-treated breast cancer patients." (PMID 40544998, 2025). "BET inhibitors are commonly used chemotherapy drugs in breast cancer treatment, and NR5A2 and NCOA3 mainly mediate their resistance." (PMID 39664391, 2024). "To further assess the relevance of NR5A2 to human breast cancer, we generated an Oncoprint across breast tumors from the METABRIC study." (PMID 38994678, 2024). "Using small molecule inhibitors to target NR5A2 or NCOA3 can significantly enhance the anti-cancer effects of BET inhibitors in breast cancer in vitro and in vivo." (PMID 39664391, 2024). "A previous study on breast cancer reported that NR5A2 expression was higher in the cancer tissues compared to healthy tissues." (PMID 38358044, 2024). "Reorganization of the actin cytoskeleton and cleavage of E‐cadherin also enhance the malignant behavior of NR5A2‐overexpressing breast cancer cells." (PMID 38358044, 2024). "MaPR172H/− and MaPR245W/− mammary tumor lysates were immunoprecipitated with an Nr5a2 antibody or IgG." (PMID 38994678, 2024).
breast carcinoma (continued). "In breast cancer, an increased NR5A2 expression has been reported in tumor-adjacent adipose tissue as compared to normal breast tissue both from cancer-free patients and from breast cancer patients." (PMID 36140779, 2022). "For example, the abundance of the transcript for Cdkn1a, the cyclin dependent kinase inhibitor, is increased in PND4 cKO mice in the present study, consistent with its regulation by NR5A2 in breast cancer cells." (PMID 33441767, 2021). "This study aims to determine LRH-1/NR5A2 expression in breast cancers and relationship with DNA methylation and tumour characteristics." (PMID 29137369, 2017). "All these results suggested that miR-27b-3p attenuated breast cancer cell resistance to TAM by repressing NR5A2 and CREB1." (PMID 27809310, 2016). "In this study, we demonstrate the clinical importance of NR5A2 relative to its prognostic role in breast cancers." (PMID 26366408, 2015). "This is the first report where NR5A2-mediated signature is a poor prognostic indicator in a subset of breast cancers." (PMID 26366408, 2015). "NR5A2 is a direct estrogen receptor α (ERα) target gene, its expression correlates with ERα in breast tumours and it promotes breast cancer proliferation and invasion." (PMID 25514243, 2014). "Additionally, NR5A2 is also highly expressed in adriamycin‐resistant breast cancer cells, and the silencing of NR5A2 expression leads to the reversal of cellular resistance." (PMID 38358044, 2024). "Thus, it is possible that hormone receptors direct NR5A2 to mediate distinct transcriptional landscapes in breast cancer." (PMID 38994678, 2024). "While NR5A2 mRNA was associated with ER status in invasive breast cancer, post-translational regulation of LRH-1 protein may affect such associations with breast cancer characteristics." (PMID 29137369, 2017). "The significance and regulation of liver receptor homologue 1 (LRH-1, NR5A2), a tumour-promoting transcription factor in breast cancer cell lines, is unknown in clinical breast cancers." (PMID 29137369, 2017). "Furthermore, we demonstrated that the reduction of miR-27b-3p conferred resistance to tamoxifen in breast cancers by increasing the NR5A2 and CREB1 levels." (PMID 27809310, 2016). "In ER+/ and ER− /breast-cancer cells, NR5A2 is a mitogen and this action may involve NR5A2-dependent stimulation of Growth-Regulation-by-Estrogen-in-Breast-cancer-1 (GREB-1) transcription." (PMID 26894976, 2016). "Relative to therapeutic potential, NR5A2 may be a new target for the effective treatment of a subset of breast cancers with the 15-gene signature." (PMID 26366408, 2015). "NR5A2 may be a potential drug target for treating a subset of breast cancer tumors across breast cancer subtypes, especially ER(−) breast tumors." (PMID 26366408, 2015). "NR5A2 may aid breast cancer progression in postmenopausal women by promoting local oestrogen biosynthesis." (PMID 25514243, 2014). "Additionally, higher levels of NR5A2 were also detected in adriamycin‐resistant breast cancer cells, and the overexpression of NR5A2 in breast cancer cells and transplanted tumors in nude mice led to an attenuation in the effects of adriamycin and cisplatin on the cancer cells." (PMID 38358044, 2024). "For example, microRNA‐27b‐3p directly targets NR5A2 and CREB1 to enhance tamoxifen‐induced breast cancer cell toxicity." (PMID 36303447, 2022). "Lastly, miR-27b-3p levels were found to be significantly negatively correlated with both NR5A2 and CREB1 levels in breast cancer tissues." (PMID 27809310, 2016). "Results showed NR5A2, CREB1 and GOLM1 expression levels were significantly higher in tamoxifen-resistant breast cancer cells." (PMID 27809310, 2016).
breast carcinoma (continued). "The group of NRs endowed with potential oncogenic properties in breast-cancer is smaller and consists of the Lipid-Sensors, NR1C2 and NR1I2, the Enigmatic-Orphans, NR1F3, NR3B1 and NR5A2, as well as the Orphan-Receptors, NR2E1, NR2E3 and NR6A1." (PMID 26894976, 2016). "Our results showed that miR-27b-3p mimics significantly attenuated both protein and mRNA levels of NR5A2 and CREB1, whereas miR-509-5p inhibitors observably enhanced the protein and mRNA levels of the two genes in all the four breast cancer cells." (PMID 27809310, 2016). "Finally, NR5A2 may represent a negative prognostic marker, as a target-genes signature is associated with poor outcome in high-grade mammary-tumors." (PMID 26894976, 2016). "In this report we analysed the effect of the orphan nuclear receptor NR5A2 (also termed Liver Receptor Homolog-1, LRH-1) on the transcriptional regulation of Growth Regulation by Estrogen in Breast Cancer (GREB1) and breast cancer proliferation." (PMID 22359603, 2012). "Twenty-three percent of these breast cancers harbor an amplification of NR5A2; no tumors have NR5A2 deletions." (PMID 38994678, 2024). "Moreover, research has shown that BET inhibitors (JQ1 and I-BET151) exert anti-cancer effects in breast cancer by inducing ferroptosis, with NCOA3, as a coactivator, interacting with NR5A2 to counteract BETi-induced ferroptosis." (PMID 39867656, 2024). "More importantly, we validated that miR-27b-3p directly targeted and inhibited the expression of nuclear receptor subfamily 5 group A member 2 (NR5A2) and cAMP-response element binding protein 1 (CREB1) and therefore augmented tamoxifen-induced cytotoxicity in breast cancer." (PMID 27809310, 2016). "To further examine whether miR-27b-3p levels were correlated with NR5A2 and CREB1, we analyzed NR5A2 and CREB1 mRNA levels in 32 breast cancer tissues from tamoxifen-untreated patients and 20 breast cancer tissues from tamoxifen-resistant patients by RT-PCR." (PMID 27809310, 2016). "MaPR172H/− and MaPR245W/− mammary tumor-derived cell lines were transfected with either Nr5a2 siRNAs (si-1, si-2, si-3, and si-4) or universal nontargeting control siRNA (J-047044-09-0010, J-047044-10-0010, J-047044-11-0010, J-047044-12-0010, and D-001810-10-20, respectively, Horizon Discovery)." (PMID 38994678, 2024). "Furthermore, we validated that miR-27b-3p directly targeted and inhibited the expression of nuclear receptor subfamily 5 group A member 2 (NR5A2) and cAMP-response element binding protein 1 (CREB1) and therefore augmented tamoxifen-induced cytotoxicity in breast cancer." (PMID 27809310, 2016). "NR5A1 has never been the object of studies in breast-cancer while data on NR5A2 are available." (PMID 26894976, 2016).